RNU6-1153P (RNA, U6 small nuclear 1153, pseudogene)
Gene: Small nuclear RNA gene on chromosome 16 (53,443,228 to 53,443,332, reverse strand). Ensembl gene ENSG00000252569.
Homologues: Orthologues: chimpanzee U6 (97% identical), macaque U6 (90% identical). Paralogues in human: RNU6-209P (75% identical), RNU6-25P (75% identical), RNU6-38P (75% identical), RNU6-658P (75% identical), RNU6-1 (74% identical), RNU6-1180P (74% identical), RNU6-11P (74% identical), RNU6-1340P (74% identical), RNU6-2 (74% identical), RNU6-37P (74% identical), RNU6-3P (74% identical), RNU6-468P (74% identical), and 1286 more.